ZC3H14 (zinc finger CCCH-type containing 14)
Description:
RNA-binding protein involved in the biogenesis of circular RNAs (circRNAs), which are produced by back-splicing circularization of pre-mRNAs. Acts by binding to both exon-intron boundary and 3'-UTR of pre-mRNAs to promote circRNA biogenesis through dimerization and the association with the spliceosome. Required for spermatogenesis via involvement in circRNA biogenesis. Regulates the pre-mRNA processing of ATP5MC1; preventing its degradation. Also binds the poly(A) tail of mRNAs; controlling poly(A) length in neuronal cells.
Synonyms: MSUT-2; FLJ11806; UKp68; NY-REN-37; MRT56; SUT2
Tractability: PROTAC: UniProt records ubiquitination sites on it; ubiquitination databases record sites on it; its protein half-life has been measured.
Gene: Protein-coding gene on chromosome 14 (88,562,948 to 88,627,596, forward strand). Ensembl gene ENSG00000100722.
Subcellular location: Nucleus speckle; Nucleus speckle (Isoform 1); Nucleus speckle (Isoform 3); Cytoplasm (Isoform 6)
Subcellular location (Human Protein Atlas): Nuclear speckles; Nucleoli; Nucleoli rim
Gene Ontology:
Molecular function: mRNA 3'-UTR binding; pre-mRNA binding; protein binding; RNA binding; poly(A) binding; metal ion binding
Biological process: mRNA stabilization; spliceosome-depend formation of circular RNA; regulation of mRNA stability; spermatogenesis
Cellular component: axon cytoplasm; cytoplasm; dendrite cytoplasm; nuclear speck; nucleus; ribonucleoprotein complex
Genetic constraint (gnomAD): Loss-of-function variants: 30 observed, 91.15 expected, observed/expected ratio (o/e) 0.33, 90% interval 0.25 to 0.45. The upper end of that interval is the gene's LOEUF score, 0.45, which puts it in group 1 of 6, group 1 being the genes least tolerant of losing a copy. Missense variants: 763 observed, 920.84 expected, observed/expected ratio (o/e) 0.83, 90% interval 0.78 to 0.88. Synonymous variants: 315 observed, 310.84 expected, observed/expected ratio (o/e) 1.01, 90% interval 0.92 to 1.11.
Gene-disease validity (ClinGen):
ClinGen rates the evidence that ZC3H14 causes each of these diseases.
intellectual disability (autosomal recessive): Limited.
Homologues: Orthologues: chimpanzee ZC3H14 (99% identical), macaque ZC3H14 (99% identical), pig ZC3H14 (94% identical), guinea pig ZC3H14 (93% identical), dog ZC3H14 (92% identical), mouse Zc3h14 (90% identical), rat Zc3h14 (90% identical), rabbit ZC3H14 (89% identical), tropical clawed frog ZC3H14 (50% identical), zebrafish zc3h14 (44% identical), Drosophila melanogaster Nab2 (28% identical), Caenorhabditis elegans sut-2 (24% identical).
Diseases named in the same sentence as ZC3H14 in open-access papers:
ZC3H14 is named in the same sentence as 18 diseases in open-access papers, as found by Europe PMC text mining. Sharing a sentence is not in itself a finding about the gene and the disease. The quoted sentences say what the papers report.
Intellectual disability (7 papers, 2019 to 2025). "ZC3H14 is broadly expressed in many tissues and cell types but mutations in the human ZC3H14 gene are associated with a heritable form of intellectual disability, implying an important requirement for this protein in the central nervous system." (PMID 37458420, 2023). "The human ZC3H14 gene encodes a ubiquitously expressed polyadenosine RBP that is lost in a heritable nonsyndromic form of intellectual disability." (PMID 34139237, 2021). "Inactivating mutations in the human ZC3H14 gene, which encodes a ubiquitously expressed poly(A) RNA-binding protein, are linked to a monogenic form of intellectual disability." (PMID 32817074, 2020). "Likewise, in mouse models, loss of functional Zc3h14 impairs neuronal development and disrupts spermatogenesis, whereas loss-of-function mutations in human ZC3H14 lead to intellectual disability." (PMID 40846642, 2025). "The human ZC3H14 gene, which encodes a ubiquitously expressed polyadenosine zinc finger RNA-binding protein, is mutated in an inherited form of autosomal recessive, nonsyndromic intellectual disability." (PMID 34139237, 2021). "Importantly, mutations in the gene encoding the human Nab2 orthologue ZC3H14 and cause intellectual disability." (PMID 30578643, 2019). "The human ZC3H14 gene encodes a ubiquitously expressed zinc-finger, polyadenosine RBP (ZnF CysCysCysHis #14) that is lost in an inherited form of intellectual disability." (PMID 35471546, 2022). "One such RNA-binding protein is ZC3H14, which is lost in an inherited intellectual disability." (PMID 35471546, 2022). "This hypothesis is significant given that very few Nab2-target mRNAs are known and the Nab2 human ortholog ZC3H14 is lost in an inherited form of recessive intellectual disability." (PMID 32817074, 2020).
cognitive defects (3 papers, 2019 to 2024). "Fly models of cognitive disorders, such as fragile X syndrome (FXS) or Alzheimer’s disease, or of inherited cognitive deficits, for example caused by mutation of ZC3H14, show subtle MB defects." (PMID 31138234, 2019).
autosomal recessive intellectual disability (2 papers, 2019 to 2020). "Mutations in the gene encoding the ubiquitously expressed RNA-binding protein ZC3H14 result in a non-syndromic form of autosomal recessive intellectual disability in humans." (PMID 32817074, 2020).
Dias-Logan syndrome (1 paper, 2021). Any BAFopathy in which the cause of the disease is a mutation in the BCL11A gene.
epilepsy (1 paper, 2021). A brain disorder characterized by episodes of abnormally increased neuronal discharge resulting in transient episodes of sensory or motor neurological dysfunction, or psychic dysfunction. "We observed a reduction of Cstb, Jam3, Zc3h14, and Msn, which can cause neuroinflammation and epilepsy (Cstb), blood-brain-barrier disruption (Jam3), impairment of synaptic function (Zc3h14) and long-term memory (Msn)." (PMID 35155612, 2021).
neoplasm (1 paper, 2023). A benign or malignant tissue growth resulting from uncontrolled cell proliferation. "The results showed that ASEs up-regulated in BLCA with high-level neoplasm grade were enriched to several RBPs’ motifs, including “poly-T” motifs and polypyrimidine tract (Py-tract) sequence of HuR, CPEB4, TIA1, HNRNPC, PTBP1, RALY and ZC3H14, and motifs of PCBP2 and SNRNP70." (PMID 37810965, 2023).
neurodegenerative disease (1 paper, 2021). A disorder of the central nervous system characterized by gradual and progressive loss of neural tissue and neurologic function. "We previously identified mRNA transcripts regulated by ZC3H14–THOC binding in which dysfunction is linked to neurodegenerative disease, including postsynaptic density protein 95 (Psd95), ATP synthase lipid-binding protein (Atp5g1), and microtubule-associated protein tau (MAPT)." (PMID 33234594, 2021).
ZC3H14 also shares sentences with these, for which no sentence is quoted: tauopathies (2 papers); brain malformations (1); cognitive decline (1); corticobasal degeneration (1); fragile X syndrome (1); melanoma (1); microencephaly (1); multiple system atrophy (1); oculopharyngeal muscular dystrophy (1); Parkinson disease (1); proteinopathy (1).